LPL (lipoprotein lipase)
Diseases named in the same sentence as LPL in open-access papers (continued):
Sharing a sentence is not in itself a finding about the gene and the disease.
type I hyperlipoproteinemia (continued). "Familial lipoprotein lipase deficiency (LPLD, sometimes known as chylomicronaemia syndrome) is caused by loss-of-function mutations in genes involved in the lipoprotein lipase pathway and is the result of autosomal recessive inheritance." (PMID 28927429, 2017). "The discrepancy between hyperchylomicronemia and normal LPL activities raises the question of the role of additional regulators of heparin releasable LPL and/or molecular mechanisms leading to transient LPL deficiencies." (PMID 24788417, 2014). "In this group, most patients (13/15) presented normal LPL activity whereas 2 patients had both a very low LPL activity (1.6 and 3.7 μmol/l/min) and a clear familial history of hyperchylomicronemia." (PMID 24788417, 2014). "Determination of lipoprotein lipase (LPL) activity is important for hyperchylomicronemia diagnosis, but remains both unreliable and cumbersome with current methods." (PMID 24788417, 2014). "Persistent chylomicronemia is caused by lipoprotein lipase deficiency (LPLD) or lack of lipoprotein lipase (LPL) bioavailability." (PMID 40046103, 2025). "LPL gene - lipoprotein lipase, Apo CII and familial dyslipidemia type O or familial chylomicronemia." (PMID 30345000, 2017).
pancreatitis (44 papers, 2004 to 2025). Inflammation of the pancreas. "The drug‐target analyses suggest that targeting APOB, APOC3, and LPL are promising strategies to reduce the risk of multiple forms of pancreatitis, a finding that warrants further investigation." (PMID 41403918, 2025). "These analyses collectively establish distinct causal mechanisms through which APOC3, APOB, and LPL contribute to pancreatitis risk." (PMID 41403918, 2025). "LPL deficiency typically manifests in childhood, with abdominal pain, recurrent pancreatitis, eruptive cutaneous xanthomas, and hepatosplenomegaly." (PMID 40142634, 2025). "Encouragingly, a recent observational open‐label n‐of‐1 study conducted in a paediatric patient harbouring null/null variants in LPL also showed that Volanesorsen effectively lowered TG levels by>70% and prevented hospital admissions for pancreatitis." (PMID 38974610, 2024). "Patient 4 from our study with c.337T>C (p.Trp113Arg) homozygous LPL variant presented with recurrent pancreatitis." (PMID 38911039, 2024). "In 2012, gene therapy was developed for a subset of patients with LPL deficiency who were at an increased risk of pancreatitis." (PMID 37630727, 2023). "Compared clinical characteristics of patients carried LPL c.590G > A mutation, age and TG level were in a big different, also the history of pancreatitis were different." (PMID 35368694, 2022). "Patients with GPIHBP1 deficiency express a similar phenotype as patients with LPL deficiency, such as severe chylomicronemia (plasma TG levels above 1,500 mg/dl (16.9 mmol/L) presented already in childhood and high risk of pancreatitis." (PMID 36051701, 2022). "Recently adeno-associated virus type I LPL gene therapy was approved in Europe for the treatment of FCS in a subset of patients with recurrent pancreatitis." (PMID 25889044, 2015). "Accurately quantifying the function and activity of LPL may guide the diagnosis of LPL deficiency to highlight individuals at risk of severe and life-threatening complications such as pancreatitis, and therefore need to be followed more closely." (PMID 35911520, 2022). "All FCS causing genes, including LPL are well-documented pancreatitis susceptibility genes." (PMID 24795752, 2014). "When HTG is caused by rare monogenetic mutations in genes like lipoprotein lipase (LPL), the main enzyme that hydrolyzes plasma TG, or apolipoprotein C-II (apoC-II), an activator of LPL, larger lipoprotein TG-rich particles tend to accumulate and these patients are at a risk for pancreatitis." (PMID 30863636, 2019). "Biallelic pathogenic variants in LPL or APOC2 accounted for <5% of all cases but were associated with the most extreme phenotypes (mean TG > 2800 mg/dL) and the highest burden of pancreatitis (>70% with ≥1 prior episode)." (PMID 41300829, 2025). "FCS due to biallelic LPL, APOC2, GPIHBP1, or LMF1 variants accounted for <5% of cases and showed extreme TG elevations (>2800 mg/dL) with pancreatitis prevalence (>70%)." (PMID 41300829, 2025). "Since then, ApoC-II variants that lead to compromised LPL function have been associated with HTG, pancreatitis, familial chylomicronemia, and gestational HTG and pancreatitis." (PMID 35911520, 2022). "Loss-of-function mutations in LPL cause increased triglycerides, CVD risk, chylomicronemia, and pancreatitis." (PMID 35230602, 2022). "In the current study, the results of TPE, which is a rapid, effective, and safe treatment modality in patients with pancreatitis secondary to HTG, were evaluated, and the frequency of LPL mutation in these patients was determined." (PMID 31203594, 2019). "Insulin and heparin can be used to increase LPL activity during the acute phase in patients with pancreatitis secondary to HTG." (PMID 31203594, 2019). "Nevertheless, patients did experience persistent LPL activity, sustained improvements in postprandial chylomicron metabolism and decreased incidence of pancreatitis one year following infection." (PMID 29304082, 2018).
pancreatitis (continued). "LPL gene replacement therapy has recently been approved in Europe, although its use is currently restricted to the most severely affected patients with FCS due to an LPL gene defect and recurrent pancreatitis." (PMID 25889044, 2015). "In this sample, we observed important variations in term of pancreatitis morbidity (assessed by the recurrence of hospitalizations), despite the fact that all patients were carrying the same LPL gene defect." (PMID 24795752, 2014). "Primary defects in LPL and C-II are rare in survivors of acute hypertriglyceridaemic pancreatitis; lipase activity measurements should be restricted to those having their first episode during chilhood." (PMID 19534808, 2009). "Acquired LPL inhibition, as a rare complication of COVID-19, due to overproduction of autoantibodies may increase the incidence of pancreatitis by 360-fold, with poor prognosis once pancreatitis is present." (PMID 38449886, 2024). "Particularly, variants in the lipoprotein lipase (LPL) gene and its molecular regulating genes could cause chylomicronemia and recurrent pancreatitis." (PMID 37768328, 2023). "Nonetheless, LPL replacement could be used to lower triglycerides and protect these patients from life-threatening pancreatitis." (PMID 35230602, 2022). "Numerous novel therapies on the horizon that reduce TG by decreasing the activity of proteins that inhibit lipoprotein lipase such as apolipoprotein C-III and ANGPTL 3/4, including Volanesorsen (ASO Apo CIII) approved in Germany for FCS with high risk of pancreatitis, offer promise for the future." (PMID 34805377, 2021). "LPL-deficient mice differ from LPL-deficient humans in that they do not develop pancreatitis even when very high plasma TG levels are present." (PMID 32849290, 2020). "Additionally, the severe hypertriglyceridemia mainly contains CM that leads to pancreatitis, and the hydrolysis of CM via LPL results in the production of free fatty acids and chylomicron remnants which can contribute to pancreatitis." (PMID 29212549, 2017). "In addition, she had excellent weight gain, linear growth, up-to-age developmental milestones, and no further episodes of pancreatitis or other LPL-deficiency-related complications." (PMID 37630727, 2023). "Additionally, no case of LPL deficiency was reported among 27 adults with hypertriglyceridaemic pancreatitis." (PMID 19534808, 2009). "Furthermore, as Pruneta-Deloche and colleagues note, the autoantibodies against LPL observed in patients with autoimmune disease seem to only result in a ~10% elevation in plasma TG levels, which on its own would be insufficient to induce the severe HTG required to cause pancreatitis." (PMID 39858602, 2025). "Other than clinical presentation, including severely elevated triglyceride levels, recurrent pancreatitis, and xanthomas, the diagnosis of FCS relies on genetic testing, lipoprotein lipase activity, and a recently validated FCS clinical scoring system." (PMID 39574983, 2024). "This may be because of a physiological reduction in lipoprotein lipase (LPL) activity during the third trimester, which has profound implications for individuals with LPL deficiency leading to an exceptionally high risk of pancreatitis in the third trimester and peripartum." (PMID 38974616, 2024). "Any pathogenic variation in the LPL gene results in the reduction or absence of LPL activity, resulting in higher TG levels in plasma, which in turn leads to the accumulation of TGs in various tissues resulting in pancreatitis, eruptive xanthomas, and hepatosplenomegaly." (PMID 38911039, 2024). "LPL–GPIHBP1 fusion protein has properties that favor its development as an agent for the treatment and prevention of hyperlipidemic pancreatitis and/or abdominal pain attacks." (PMID 31645434, 2020). "LPL–GPIHBP1 has the potential to be effective in treating and preventing abdominal pain and hyperlipidemic pancreatitis by acutely lowering plasma TG." (PMID 31645434, 2020).
pancreatitis (continued). "By the contrary, the acute phase of pancreatitis is not the best clinical scenario to measure LPL activity (pain, nasogastric tube, prophilactic heparin, inflammatory state..)." (PMID 19534808, 2009). "The pathogenesis of pancreatitis is not well elucidated, and some researchers have mentioned that capecitabine may reduce the activity of lipoprotein lipase and hepatic triglyceride lipase." (PMID 24041405, 2013).
acute pancreatitis (36 papers, 2009 to 2026). An acute inflammatory process that leads to necrosis of the pancreatic parenchyma. "LPL dysfunction leads to familial LPL deficiency, which is characterized by chylomicronemia and high risk for acute pancreatitis." (PMID 42165204, 2026). "LPL deficiency should be suspected in individuals younger than 40 years of age presenting with recurrent acute pancreatitis, eruptive cutaneous xanthomas, and hepatosplenomegaly." (PMID 40142634, 2025). "Heterozygous patients have a range of symptoms, while homozygous LPL deficiency presents with severe symptoms including acute pancreatitis, xanthomas, and lipemia retinalis." (PMID 38911039, 2024). "For the fifteen LPL pathway variants previously used as the instrumental variable of TG to acute pancreatitis, only 12 of them were available in the GLGC summary statistics without the UK Biobank." (PMID 38491158, 2024). "Homozygous patients with pathogenic LPL variants c.337T>C had a higher likelihood of experiencing acute pancreatitis, while compound heterozygous and heterozygous patients seemed to experience milder or no complications." (PMID 38911039, 2024). "Some experienced episodes of abdominal pain and recurrent acute pancreatitis, a common LPL deficiency complication." (PMID 37630727, 2023). "To date, more than 200 LPL mutations or single-nucleotide polymorphisms (SNPs) have been reported to cause severe hypertriglyceridemia syndrome and recurrent acute pancreatitis." (PMID 29921298, 2018). "In fact, a complete absence of LPL activity with a massive accumulation of chylomicrons in the plasma can result in familial LPL deficiency, a rare autosomal recessive disorder characterized by abdominal pain, acute pancreatitis, hepatosplenomegaly, and eruptive cutaneous xanthomata." (PMID 35456470, 2022). "Overproduction of these particles exacerbates functional LPL insufficiency, impairing TG-rich lipoproteins clearance and promoting hyperglycemia, acute pancreatitis, and cardiovascular complications." (PMID 41393592, 2025). "TPE can also achieve therapeutic exchange of plasma for HTG-induced acute pancreatitis, using free fatty acids, apolipoproteins, and lipoprotein lipase supplemented by donors to aid in the metabolism of TG-rich lipoproteins." (PMID 41393592, 2025). "The study aims to explore the relationship between lipoprotein lipase (LPL) variants and hyperlipidemic acute pancreatitis (HLAP) in the southeastern Chinese population." (PMID 38530959, 2024). "All exons and flanking intronic regions of LPL were Sanger sequenced in patients with HTG-related acute pancreatitis (HTG-AP) or HTG-AP in pregnancy." (PMID 37568214, 2023). "In this study, the mother and daughter had the same LPL genotype with compound heterozygous mutations of A98T and L279V; thus, both manifested massive HTG and acute pancreatitis." (PMID 24646025, 2014). "In the current study, we showed two-related patients who manifested massive HTG and acute pancreatitis with a low LPL post-heparin activity." (PMID 24646025, 2014). "The data from this study showed that compound heterozygote mutations of A98T and L279V inactivate lipoprotein lipase enzymatic activity and contribute to severe HTG and acute pancreatitis in two Chinese patients." (PMID 24646025, 2014). "In this study, we described a novel LPL gene missense mutation (L279V) in two Chinese patients with severe HTG and acute pancreatitis." (PMID 24646025, 2014). "This study reported on two patients in a Chinese family with LPL gene mutations and severe HTG and acute pancreatitis." (PMID 24646025, 2014). "Quantification of the LPL mass and activity should therefore be reserved for patients with a normal body mass index and recurrent acute pancreatitis that started in childhood or adolescence." (PMID 19534808, 2009).
acute pancreatitis (continued). "Chinese patients with HTG-associated acute pancreatitis (HTG-AP) were screened for rare nonsense, frameshift, missense or canonical GT-AG splice site variants in LPL and four other lipid metabolism-related genes (APOC2, APOA5, GPIHBP1 and LMF1) by Sanger sequencing." (PMID 37550668, 2023). "Loss of LPL activity by genetic variants, in either LPL itself or in its supporting proteins, results in prolonged presence of VLDL in the circulation, which is related to increased CVD risk and increased risk for acute pancreatitis." (PMID 34440342, 2021).
breast carcinoma (34 papers, 2013 to 2025). "Which found protein truncating variants in PALB2 associated with breast cancer diagnosis and a family history of breast cancer, and protein truncating variants in LPL associated with decreased risk for high cholesterol." (PMID 32678846, 2020). "In this hypothesis article, we introduce LPL, provide a meta‐analysis of RNAseq data showing that LPL is associated with poor prognosis, and explain how LPL might play a role in breast cancer prognosis over time." (PMID 36652113, 2023). "Regarding breast cancer, LPL contributes to the energy supply of tumor cells by hydrolyzing lipids from lipoproteins, potentially facilitating tumor growth and progression." (PMID 40625358, 2025). "These targeted miRNAs are important regulators involved in the development and metastasis of breast cancer that are mainly associated with the change in expression of PCK1 and LPL." (PMID 38791477, 2024). "Lipoprotein lipase (LPL) was identified as a pharmacodynamic biomarker for tumors especially in aggressive breast cancer." (PMID 38430429, 2024). "LPL plays a major role in influencing breast cancer liver metastasis because it affects the rates of lipid metabolism." (PMID 38791477, 2024). "This study’s integrative approach unveiled metabolic reprogramming, suggesting altered PCK1 and LPL expression as key in breast cancer metastasis recurrence." (PMID 38791477, 2024). "The result also showed that downregulated genes SFRP2 and LPL were positively correlated in all breast cancer subtype groups." (PMID 38791477, 2024). "Hsa-miR-124-3p can block the LPL function and therefore inhibit the lipid metabolism and the cell energy homeostasis of the breast cancer cells, which would be a strategy to control its metastasis." (PMID 38791477, 2024). "The analysis conducted through Gepia 2.0 further demonstrated the expression of SFRP2 and LPL in different breast cancer subtype groups." (PMID 38791477, 2024). "Contributing to the growth and proliferation of breast cancer cells is the presence of lipoprotein lipase (LPL) in their microenvironment, resulting in an increased delivery of free fatty acids (FFA) for energy production via β-oxidation." (PMID 34404457, 2021). "Increased expression of LPL occurs in breast cancer, non-small cell lung cancer, and chronic lymphocytic leukemia, with breast cancer also exhibiting increased CD36 expression." (PMID 33946927, 2021). "LPL gene expression has been detected in select human breast cancer cell lines, and LPL protein and activity were identified in the Du4475 cell line and primary breast tumor tissues." (PMID 34404457, 2021). "Mounting evidence showed that LPL-mediated extracellular lipolysis occurs in breast cancer, liposarcomas and liver steatosis, which expression was considered to increase the free FA content." (PMID 34976793, 2021). "Collectively, our data suggest that components within total lipoprotein lipid hydrolysis products generated by LPL change the cytokine secretion profile of breast cancer cells in a subtype-specific manner." (PMID 34404457, 2021). "Our objective was to examine cytokine secretion profiles from different breast cancer cell lineages in response to total lipoprotein hydrolysis products generated by LPL." (PMID 34404457, 2021). "The glycosylphosphatidylinositol high-density lipoprotein binding protein 1 (GPIHBP1) acts to chaperone secreted LPL and interact in fatty acids and breast cancer." (PMID 31182966, 2019). "Triple-negative breast cancer cell lines express lipoprotein lipase (LPL) and fatty acid synthase, both enzymes participating in lipolysis through the CD36 pathway, which transports fatty acids into the cell." (PMID 30404206, 2018). "Lipid uptake is also an important feature as breast and liposarcoma cell linesproduced CD36 (FA translocase) and lipoprotein lipase (LPL), the latter associatedwith an aggressive basal gene expression in breast cancer." (PMID 29026007, 2017).